CASP8 (caspase 8)
Diseases named in the same sentence as CASP8 in open-access papers (continued):
Sharing a sentence is not in itself a finding about the gene and the disease.
tumor (continued). "In contrast to that in the tumor adjacent normal tissue, the expression levels of cleaved caspase-3, caspase-3, caspase-8 and caspase-9 were significantly higher in tumor tissues (all p<0.001, Wilcoxon signed-rank test), suggesting that these caspases might be associated with tumor transformation." (PMID 28700659, 2017). "In that context, we here demonstrate a highly significant correlation between Plk3 and pT273 caspase-8 detection and thus phosphorylation of caspase 8 may represent a mechanism by which different levels of Plk3 expression in tumor cells may stimulate the extrinsic apoptotic machinery." (PMID 27462786, 2016). "Importantly, reversal or inhibition of caspase-8 phosphorylation may prove a valuable avenue to explore for sensitization of resistant tumours to extrinsic apoptotic stimuli." (PMID 27109099, 2016). "Of note, we analyzed 41 representative blood samples from the patients in our cohort and observed that all these patients have the same SNP status in their blood as in their tumor (data not shown), indicating that CASP8 SNP D302H is a germline risk factor for NB patients with MYCN amplification." (PMID 25502557, 2014). "The incoherent pattern of the CASP8 mRNA and protein expression levels in this study suggested that a post-transcriptional regulation, such as excessive ubiquitin of CASP8 protein in tumor tissue and/or miRNA regulation, may play a crucial role in the development of CRC." (PMID 23844036, 2013). "However, patient number with a nuclear caspase-8 score ≥10.3 might be too small (n = 10) for a multivariate analysis of the two parameters, high nuclear caspase-8 and tumor grading." (PMID 24209510, 2013). "Furthermore, increase in the expression of other molecules associated with the Fas receptor such as Traf1 and Fas (TNFRSF6)-associated via death domain (FADD) leading to activation of caspase-8 was also observed in PC3 cells and/or tumor lysates with simvastatin treatment." (PMID 22974127, 2012). "Recently, it has been shown that TRAIL receptors and caspase 8 are significantly down-regulated in high grade and metastatic head and neck squamous cell carcinoma, suggesting that the level of tumor cell resistance to TRAIL might increase with tumor progression." (PMID 21264227, 2011). "c-FLIP and caspase-8 signaling have recently been shown to play a role in the proliferation of B-lymphocytes and in invasive processes of tumor cells, and stimulation of these processes might also confer a selective advantage to tumor cells." (PMID 24281211, 2010). "It is possible that in primary tumors caspase-8 predominantly contributes to apoptosis and therefore can prevent metastasis, but in those tumor cells that escape apoptosis (i.e., are resistant to apoptosis), caspase-8 may be contributing to migration and metastasis." (PMID 20808443, 2010). "The activation of caspase 8 and its downstream effectors may be a general effect of PL on tumours." (PMID 17262078, 2007). "Thus, the potential therapeutic use of rCD40L in NB patients may depend on preliminary in vitro assessment of caspase-8 activation in tumour cells under baseline conditions and following culture with demethylating agents or IFN-γ." (PMID 12771917, 2003). "Beclin 1, a tumor suppressor that interacts with Bcl-2, Bax, BAK, Casp8, and Bcl-XL, and triggers apoptosis and induces autophagy, was significantly increased in 60H muscle compared to that in age-matched wild-type mice." (PMID 41507123, 2026). "For instance, activation of caspase-8 by metabolite α-ketoglutarate or TNF-α leads to GSDMC cleavage and subsequent induction of pyroptosis in tumor cells." (PMID 40663398, 2025).
tumor (continued). "Caspase-8 regulates apoptosis, pyroptosis and necroptosis in HCC, with dual roles in promoting tumor progression and preserving cellular homeostasis." (PMID 40555741, 2025). "The expression and functional status of critical molecules comprising the PANoptosome, including ZBP1, RIPK1, RIPK3, CASP8, and ASC, can have a bidirectional impact on tumor survival, immune recognition, or tumor cell death." (PMID 40422233, 2025). "To test this idea, we treated CD4+ T cells with tumor tissue supernatant during their in vitro activation, and found that cleavage of GSDMD and of caspase-8 were both weakened, leading to reduced production of IL-2." (PMID 40759573, 2025). "Compared to other conjugates, the GQD_Caspase-8 conjugate exhibited superior anticancer and neuroprotective efficacy in the GBM tumor-bearing rat model." (PMID 40922752, 2025). "PARP inhibitors (PARPis) induce a specific type of pyroptosis in ovarian cancer cells via the TNF-caspase 8-GSDMD/E axis, enhancing TIME and promoting tumor-targeted immune responses." (PMID 39994107, 2025). "CASP8 and PGAM5 were identified as potential biomarkers among these, while previous studies have shown that ZBP1, TLR3, and PYGL contribute to tumor progression in KIRC." (PMID 40969770, 2025). "In HCC, dysregulation of caspase-8 expression is often observed, leading to functional imbalances within HCC cells and the tumor microenvironment (TME)." (PMID 39726605, 2024). "Consistently, all doses of in vivo coffee treatment induced a significant increase in Caspase-8 and necrotic zones and a significant decrease in β- catenin, MDA, tumor volume, tumor weight, and viable tumor cell density." (PMID 39272080, 2024). "Caspase-8, which serves as a central hub in multiple signaling pathways, plays a pivotal role in the HCC TME, regulating HCC tumor immunity." (PMID 39726605, 2024). "On the other hand, caspase-8 has also been shown to act as a downstream of granzymes, specifically inducing GSDME cleavage and inducing pyroptosis, thus further activating anti-tumor immune response and inhibiting tumor growth." (PMID 38553639, 2024). "Caspase-8 phosphorylation attenuates DISC activity by inhibiting the polyubiquitination and autoproteolytic activity of caspase-8, which enhances tumor growth and migration." (PMID 38200153, 2024). "Subsequent treatment with TNF-α results in caspase-8-mediated cleavage of GSDMC, leading to pyroptosis and tumor necrosis in breast cancer." (PMID 39300122, 2024). "This study demonstrated for the first time that nuclear PD-L1, caspase-8, and GSDMC are essential for macrophage-derived TNFα-induced tumor necrosis." (PMID 38877579, 2024). "Regarding caspases, tumor cells exhibited predominantly high expression of CASP4, and immune cells showed high expression of CASP1, CASP4, and CASP8, while CASP5 plays an important role in stromal cells." (PMID 38229080, 2024). "In sum, these data establish that siα3 primes tumor cells for apoptosis via DR5 and caspase 8 activation and thereby resensitizes cells to TRAIL." (PMID 38727288, 2024). "Lower expression of HOIP can lead to increased production of caspase-3 and caspase-8 in tumor cells mediated by TNF and IFN-γ, inducing tumor cell apoptosis." (PMID 39223632, 2024). "Then, tumor growth rate, tumor necrotic area, the expression of the apoptosis-related genes CASP8, BCL-2, and BAX and the level of CASP8 protein were analyzed." (PMID 36661524, 2023). "Mice bearing M/D-driven tumors were allocated to RT, P or their combination in the optional presence of the CASP8 dimerizer AP20187, and monitored for tumor growth, progression-free survival and overall survival." (PMID 36765430, 2023).
tumor (continued). "Univariate and multivariate regression analyses showed that CASP8, GSDMC, age, and new tumor type were independent factors influencing the prognosis of patients with PAAD." (PMID 36882663, 2023). "Hypoxia in a tumor cell is related to apoptosis as hypoxia-inducible factor-alpha (HIF-α) regulates the apoptotic genes (BCL-2, BAX, caspase 3, caspase 8) as well as a survival signaling pathway, i.e., NF-kB." (PMID 36715825, 2023). "Andrographolide (ANDR) has been shown to be effective in the treatment of ovarian and breast cancers, inducing activation of caspase-8,FLIP and XIAP, promoting tumor pyroptosis and apoptosis, and inhibiting invasive metastasis." (PMID 37542283, 2023). "Combined treatment substantially increases caspase-8, caspase-3, and PARP cleavage in both cell lines and significantly suppresses tumor growth in nude mice bearing MB231 xenografts." (PMID 37559457, 2023). "After adjusting for tumor purity in TIMER, a substantial correlation was observed between CASP8 expression levels and 27 of the 44 immune cell biomarkers." (PMID 36533709, 2023). "In this study we examined the density of subtyped lymphocytes together with activation of CASP3 and CASP8 in OSCC and TILs using automated digital analysis of multiplex immunofluorescence performed on whole‐slide human tumour sections." (PMID 37443405, 2023). "A tumor-bearing mouse model was used to characterize changes in the tumor microenvironment and to explore the efficacy of ICB treatment under Casp8 knockout conditions." (PMID 36635765, 2023). "Despite similar Fas and caspase-8 expression, we observed little higher general expression of cFLIP and lower expression of RIP1 in tumor cells compared to Jurkat cells." (PMID 37838774, 2023). "We then constructed a nomogram for clinical prediction based on CASP3, CASP5, CASP8, GSDMC, age, and tumor status." (PMID 36882663, 2023). "Subsequently, we conducted clustering and LASSO analysis on each tumor and found that the inhibitory and the stimulating immune checkpoints positively correlate with ZBP1, NLRP3, CASP1, CASP8, and TNFAIP3." (PMID 38002938, 2023). "We observed a significant positive correlation between cCASP8+Tc and cCASP3+Tc levels in both the stroma and tumour islands of OSCC, consistent with CASP3 being activated downstream of CASP8 in the extrinsic pathway of apoptosis." (PMID 37443405, 2023). "When comparing the gene expression signature of poorly differentiated (G3) tumours with the moderately differentiated (G2) ones, the downregulation of RELA, NOD1, CASP8, BCL2L1, ELK1, and IKBKB was found." (PMID 36433652, 2022). "Activated caspase-8 cleaves GSDMC at D365, leading to the release of its N-terminal domain, which transforms cell apoptosis into tumor focal death." (PMID 35883480, 2022). "As for caspase-8, the prognostic/predictive value of CDK9, however, still remains controversial among different tumor types." (PMID 36428594, 2022). "In glutamine-depleted tumor cells, activation of the amino acid-sensing general control nonderepressible-2 kinase (GCN2) is responsible for TRAIL-R2 upregulation, caspase-8 activation, and apoptotic cell death." (PMID 36302756, 2022). "A decrease in the levels of RELA, NOD1, CASP8, BCL2L1, ELK1, and IKBKB was identified in the poorly differentiated (G3) tumours compared with the moderately differentiated (G2) ones." (PMID 36433652, 2022).
tumor (continued). "We further performed a meta-survival analysis based on the GENT2 database, which demonstrated that CASP8 was the only intersection gene that showed a significant difference in the expression between normal and BLCA tumor tissues (p < 0.01)." (PMID 35928267, 2022). "Treatment of Huh7 xenografts in nude mice with shikonin also showed a significantly increased activation of caspase-8, caspase-9, and PARP enzymes, but a significant decrease in tumor volume compared to control animals." (PMID 33916780, 2021). "The profiling data showed that 7 apoptosis-related genes were concordantly > twofold downregulated in recurrent tumor samples compared with the expression in paired primary tumor samples, including AKT1, BAG4, BCL2A1, BFAR, CARD6, CASP8 and TNFRSF21." (PMID 34488754, 2021). "We observed significant upregulation of the caspase 8 (CASP8) gene which is responsible for the apoptotic pathway and CDKN1C which is a tumor suppressor gene." (PMID 34885223, 2021). "Some abnormally regulated genes in our prognostic signature participated in tumour initiation and development, including NUMB, RSRC2, TMC6, CASP8, TRIO, and COMMD5." (PMID 34772375, 2021). "TAS4464 activated both caspase-8 and caspase-9 along with an increase in NOXA and a decrease in c-FLIP, resulting in complete tumor remission in a human AML xenograft model." (PMID 33420360, 2021). "Apoptosis markers, including the cleavage of caspase 8 and caspase 3 and the enzymolysis of the substrate PARP, were detected in tumor tissue, it is showed that the WB results were consistent with the experimental result in vitro." (PMID 34054543, 2021). "As previously reported, quercetin and crocetin were able to inhibit MAPK- or PI3K/AKT-mediated BCL-2 expression; promote the expression of caspase-3, caspase-8, caspase-9, and PARP so that tumor cells-cycle was inhibited, and apoptosis of tumor cell initiated." (PMID 34098848, 2021). "CTLA-4 can trigger apoptosis in CTLA-4-expressing tumour cells after the cells interact with soluble CD80 or CD86 recombinant ligands, and the induction of apoptosis occurs through a caspase-8-dependent mechanism." (PMID 31506501, 2019). "Assessing pre-treatment tumor samples, 54 patients (73%) presented with increased PLK3 expression, 33 (44.6%) with increased pT273 Caspase 8 levels, and 47 (63.5%) with high p16INK4a detection." (PMID 31475104, 2019). "The significant genes observed were PYHIN1, IKZF1, CASP8, DAPK1 and SMCHD1 expression in tumor samples." (PMID 30867653, 2019). "The Western blot data show that TRAIL and VEDT induced apoptosis (cleaved caspase-8, cleaved caspase-3, and cleaved PARP), and the combination induced greater apoptosis in the tumor tissues than either drug alone." (PMID 31367187, 2019). "In tumors, it was proposed that TNF-α signaling through TNFR2 inhibits caspase 8 activity and promotes MDSC survival and accumulation helping tumor cells to evade the immune system." (PMID 30123776, 2018). "So, to demonstrate that SCU can enhance the anti-tumor effects of BLM by promoting tumor cell apoptosis, we measured cleaved-caspase-3 and cleaved-caspase-8 activities." (PMID 29962947, 2018). "Herein, we monitored the mRNA and protein expression of caspase 3 and caspase 8 in TRAIL-sensitive and TRAIL-resistant tumor cells using real-time PCR and immunoblotting assays." (PMID 29476051, 2018). "This was accompanied by increased expression levels of cytochrome c, caspase-3, caspase-8, and caspase-9 in JHU-22miR124 cultured cells and tumor xenografts." (PMID 28212569, 2017).
tumor (continued). "And western blot analysis illustrated that cleavage of Caspase-3, PARP, Caspase-8, and Caspase-9 were significantly induced by ACT, and LC3B-I/II and Beclin 1 were also potentiated due to ACT treatment in tumor samples." (PMID 29348843, 2017). "MiR-519a-3p diminished the expression of its direct target genes for TRAIL-R2 (TNFRSF10B) and for caspase-8 (CASP8) and its indirect target gene for caspase-7 (CASP7), resulting in reduced sensitivity and tumor cell apoptosis in response to apoptotic stimuli." (PMID 28771222, 2017). "Our data suggest that at early stages of tumor growth, when p95HER2/611CTF-transformed cells start proliferating within the tumor, nutrient limitation and the likely increase in hypoxia would activate TRAIL-R/caspase-8 system and cell death." (PMID 29212182, 2017). "This includes the OPN fragments generated by caspase-8, which bear the RGD domain that was recently shown to promote tumor growth and metastasis." (PMID 27494141, 2016). "To further exploit the anti-tumor mechanism of APG and TRAIL, we detected the activation of caspase-8, caspase-9 and caspase-3." (PMID 27752089, 2016). "Subsequently, we grew the MDA-MB-361 or MDA-MB-436 cells as xenografts in nude mice, harvested tumours, extracted cells, generated spheroids and subjected them to TRAIL treatment and the Caspase-8 activity assay." (PMID 26426685, 2015). "We also observed increased apoptosis in G31P treated tumor using TUNEL staining, supported by immunoblotting analyses of apoptotic proteins such as PARP, Caspase-8, BAX, and Bcl-2." (PMID 26087179, 2015). "The expression of CD95 correlated with the expression of caspase-8, caspase-3 and PARP1 in the tumor specimens (P<0.01)." (PMID 25543761, 2015). "The authors suggested that O-glycosylation of DR4 and DR5 death receptors in various neoplasias modulates sensitivity to APO2L/TRAIL by promoting ligand-induced receptor clustering and consequent caspase-8 activation." (PMID 26309160, 2015). "c-FLIP inhibits the apoptotic signaling cascade by preventing the recruitment and activation of caspase-8 at the DISC, demonstrating that an elevated intracellular level of c-FLIP confers resistance against proapoptotic stimuli in tumor cells." (PMID 25333816, 2015). "Increased activation of caspase-8 and caspase-3, as indicated by cleaved caspase-8 and 3, was determined in tumors treated with TRA-8 combined with TMX, indicating increased tumor cell apoptosis." (PMID 26320171, 2015). "For better understanding of the mechanism of the therapeutic efficacy of BL-AD008 in our in vivo model, we examined the caspase-3, caspase-8, Bcl-2, Bax, p-AMPKα and ZIPK expressions in tumor samples immunoreactivity." (PMID 25797270, 2015). "The tumor tissues were harvested after treatment, and ACBP-L and Cisplatin treatment suppressed Bcl-2, and induced Bax, Caspase 3, and Caspase 8 molecules as detected by RT-PCR and immunohistochemistry." (PMID 24507386, 2014). "Apollon knockdown also enhanced cisplatin/docetaxel-induced activation of caspase-8 (extrinsic pathway) and caspase-9 (intrinsic pathway) in ESCC cells and xenograft tumor models." (PMID 25216531, 2014). "In the tumor panel, increased promoter methylation was observed in BLU, CASP8, DCR2, CDH1, RASSF1A and RASSF2, possibly providing the second hit for BLU, RARB and RASSF1A." (PMID 22984959, 2012). "Caspase-8 is frequently silenced in SCLC and other tumours of neuroendocrine origin, usually by aberrant promoter methylation." (PMID 20416058, 2010). "In common with other cancers, WTs also show tumour suppressor gene silencing which includes genes such as HACE1 (73% of tumours analysed), RASSF1 (56%), CASP8 (43%), MGMT (30%), RASSF5/NORE1 (15%), and CDKN2A (10–15%)." (PMID 19956686, 2009).